ECE2 (endothelin converting enzyme 2)
Description:
Converts big endothelin-1 to endothelin-1. Also involved in the processing of various neuroendocrine peptides, including neurotensin, angiotensin I, substance P, proenkephalin-derived peptides, and prodynorphin-derived peptides. May play a role in amyloid-beta processing (By similarity).
Synonyms: KIAA0604; MGC2408
Tractability: Antibody: UniProt predicts a signal peptide or a membrane-spanning region; its Gene Ontology location is reachable by antibodies, with medium confidence. PROTAC: a small molecule that binds it is known.
Target class: Metallo protease; Enzyme; Metallo protease MAE clan; Metallo protease M13 family; Protease
Gene: Protein-coding gene on chromosome 3 (184,275,531 to 184,293,031, forward strand). Ensembl gene ENSG00000145194.
Subcellular location: Golgi apparatus membrane; Cytoplasmic vesicle, secretory vesicle membrane
Pathways (Reactome):
Signal Transduction: Peptide ligand-binding receptors
Gene Ontology:
Molecular function: metalloendopeptidase activity; metallopeptidase activity
Biological process: peptide hormone processing; cell-cell signaling; G protein-coupled receptor signaling pathway; protein processing; brain development; cardioblast differentiation; heart development; proteolysis
Cellular component: cytoplasmic vesicle membrane; Golgi membrane; plasma membrane; transport vesicle membrane
Genetic constraint (gnomAD): Loss-of-function variants: 81 observed, 100.93 expected, observed/expected ratio (o/e) 0.8, 90% interval 0.67 to 0.96. The upper end of that interval is the gene's LOEUF score, 0.96, which puts it in group 4 of 6, group 1 being the genes least tolerant of losing a copy. Missense variants: 911 observed, 1,018.5 expected, observed/expected ratio (o/e) 0.89, 90% interval 0.85 to 0.94. Synonymous variants: 391 observed, 408.98 expected, observed/expected ratio (o/e) 0.96, 90% interval 0.88 to 1.04.
Homologues: Orthologues: rabbit ECE2 (96% identical), pig ECE2 (96% identical), dog ECE2 (95% identical), chimpanzee ECE2 (95% identical), macaque ECE2 (95% identical), mouse Ece2 (91% identical), rat Ece2 (90% identical), guinea pig ECE2 (89% identical), zebrafish ece2b (73% identical), tropical clawed frog ece2 (72% identical), Drosophila melanogaster Nep3 (44% identical), Drosophila melanogaster Nep4 (37% identical), and 20 more. Paralogues in human: ECE1 (62% identical), MMEL1 (38% identical), ECEL1 (37% identical), MME (33% identical), PHEX (33% identical), KEL (29% identical).
Diseases named in the same sentence as ECE2 in open-access papers:
ECE2 is named in the same sentence as 18 diseases in open-access papers, as found by Europe PMC text mining. Sharing a sentence is not in itself a finding about the gene and the disease. The quoted sentences say what the papers report.
Alzheimer disease (4 papers, 2020 to 2024). A progressive, neurodegenerative disease characterized by loss of function and death of nerve cells in several areas of the brain leading to loss of cognitive function such as memory and language. "The ECE2 gene coding variant can be used to identify Alzheimer’s disease." (PMID 36299451, 2022). "Studies have found that enzyme ECE2 has a significant role in the degradation of amyloid β as it has a significant role in Alzheimer's disease." (PMID 34532504, 2021). "ECE2 mRNA and protein levels are elevated in the temporal neocortex in Alzheimer disease; further, this has been proved by in vitro studies on SH-SY5Y where treatment with oligomer amyloid β 1-42 for 24 hours increases ECE2 mRNA, and the ECE2 gene response is upregulated in response to amyloid β." (PMID 34532504, 2021).
lung adenocarcinoma (3 papers, 2022 to 2025). A carcinoma that arises from the lung and is characterized by the presence of malignant glandular epithelial cells. "We analyzed the expression of ECE2 in lung adenocarcinoma (LUAD) and normal adjacent tissues and its relationship with clinicopathological characteristics from The Cancer Genome Atlas (TCGA) and Gene Expression Omnibus database (GEO)." (PMID 36299451, 2022). "In lung adenocarcinoma and ovarian cancer, m6A/IGF2BP1-mediated mRNA stabilizations of endothelin-converting enzyme 2 (ECE2) and circRNA nuclear factor I (circNFIX) are also crucial for tumor cells to enhance immunosuppression." (PMID 40584294, 2025).
melanoma (2 papers, 2017 to 2021). A malignant, usually aggressive tumor composed of atypical, neoplastic melanocytes. "Then, researchers transplanted melanoma cells into wild-type, EDN3-, or ECE2-deficient transgenic zebrafish and verified that variation in the tumor microenvironment exerts a tremendous impact on melanoma development and metastasis." (PMID 33644052, 2021). "Here the authors identify EDN3, and its synthetic enzyme ECE2, as a regulator of melanoma plasticity in the microenvironment." (PMID 28181494, 2017). "Prevention of this differentiated cell state via EDN3/ECE2 inactivation doubles survival of the animals, suggesting that the acquisition of a differentiated cell state is necessary for metastatic success in melanoma, and can be prevented by interrupting microenvironment-melanoma cross-talk." (PMID 28181494, 2017).
Periventricular heterotopia (2 papers, 2020 to 2021). A form of gray matter heterotopia were the mislocalized gray matter is typically located periventricularly, also sometimes called subependymal heterotopia. "ECE2 (endothelin-converting enzyme-2) has recently been found mutated in patients with periventricular heterotopia." (PMID 35069108, 2021).
autoimmune polyendocrine syndrome type 1 (1 paper, 2023). Autoimmune polyendocrinopathy type 1, or APECED syndrome, is a genetic disease that manifests in childhood or early adolescence with a combination of chronic mucocutaneous candidiasis, hypoparathyroidism and autoimmune adrenal failure. "Endothelin Converting Enzyme 2 (ECE2), an enzyme involved in neuropeptide production, is mainly located on the cytoplasm of the membrane, which is also considered to be a type of antigen for autoimmune polyendocrine syndrome type 1." (PMID 36864456, 2023).
Hyperglycemia (1 paper, 2017). An increased concentration of glucose in the blood. "A mouse study reported an association between hyperglycemia at an early stage of autoimmune diabetes and downregulation of ECE2 transcription in the kidneys." (PMID 28253288, 2017).
intrahepatic cholangiocarcinoma (1 paper, 2016). A carcinoma that arises from the intrahepatic bile duct epithelium in any site of the intrahepatic biliary tree.
lung carcinoma (1 paper, 2022). "No research has been conducted to determine the effect of endothelin-converting enzyme 2 (ECE2) in lung cancer." (PMID 36299451, 2022).
tumor (5 papers, 2021 to 2025). "Similarly, researchers separately created CRISPR-mutant zebrafish in which the function of EDN3 or ECE2 in the tumor microenvironment was lost, with both mutations exerting a severe effect on melanocyte development." (PMID 33644052, 2021). "This study confirmed ECE2 as a downstream target gene of E2F1, while the effect of ECE2 on tumor progression was rarely illustrated." (PMID 36864456, 2023). "The relationship between different immune marker genes and ECE2 expression implicates the importance of ECE2 in regulating the LUAD tumor immune microenvironment." (PMID 36299451, 2022). "To investigate the role of ECE2 in tumor immunity, we determined the correlation between ECE2 expression and immune-infiltrating cells in LUAD using the TIMER database." (PMID 36299451, 2022). "We investigated the differential expression of ECE2 in different tumor types based on bioinformatics using R software and online databases, and used immunohistochemical staining to verify the differential expression of ECE2 in LUAD tumors and adjacent tumors." (PMID 36299451, 2022). "The role of ECE2 in tumor immunity remains to be further explored, and we used GEPIA, TIMER and TCGA databases to study the correlation between ECE2 expression levels in LUAD and several markers of immune infiltration." (PMID 36299451, 2022). "In terms of methylation, the expression level of ECE2 was significantly negatively correlated with HNRNPC, IGF2BP1, IGF2BP3 and RBM15, which may affect the tumor progression of LUAD by affecting the m6A methylation level." (PMID 36299451, 2022).
cancer (2 papers, 2022 to 2023). A tumor composed of atypical neoplastic, often pleomorphic cells that invade other tissues. "Analysis of the triplet downstream data revealed that ECE2 was markedly highly expressed in cancer tissues." (PMID 36864456, 2023). "There are currently few investigations on ECE2, and its role in other cancers including LUAD remains unknown." (PMID 36299451, 2022). "We believe that the cancer-promoting role of ECE2 gene is related to the modification of m6A, which may affect the methylation level of LUAD, especially HNRNPC, through its association with HNRNPC, IGF2BP1, IGF2BP3 or RBM15, and ultimately affect the progression of LUAD." (PMID 36299451, 2022).
ECE2 also shares sentences with these, for which no sentence is quoted: adenocarcinoma (1 paper); breast carcinoma (1); cognitive deficits (1); insomnia (1); leprosy (1); ovarian carcinoma (1); sleep disorder (1); type 2 diabetes (1).